TVP23B (trans-golgi network vesicle protein 23 homolog B)
Synonyms: FAM18B; FAM18B1; CGI-148; NPD008; YDR084C
Tractability: Antibody: UniProt predicts a signal peptide or a membrane-spanning region. PROTAC: ubiquitination databases record sites on it.
Gene: Protein-coding gene on chromosome 17 (18,781,111 to 18,806,715, forward strand). Ensembl gene ENSG00000171928.
Subcellular location: Membrane
Subcellular location (Human Protein Atlas): Golgi apparatus
Gene Ontology:
Molecular function: protein binding
Biological process: vesicle-mediated transport
Cellular component: Golgi apparatus; Golgi membrane; membrane
Genetic constraint (gnomAD): Loss-of-function variants: 7 observed, 23.21 expected, observed/expected ratio (o/e) 0.3, 90% interval 0.17 to 0.57. The upper end of that interval is the gene's LOEUF score, 0.57, which puts it in group 2 of 6, group 1 being the genes least tolerant of losing a copy. Missense variants: 132 observed, 205.29 expected, observed/expected ratio (o/e) 0.64, 90% interval 0.56 to 0.74. Synonymous variants: 55 observed, 67.24 expected, observed/expected ratio (o/e) 0.82, 90% interval 0.66 to 1.02.
Homologues: Orthologues: dog TVP23B (92% identical), mouse Tvp23b (92% identical), rabbit TVP23C (91% identical), guinea pig Tvp23c (89% identical), rat Tvp23b (89% identical), rat AABR07006081.1 (85% identical), macaque TVP23B (77% identical), zebrafish tvp23b (71% identical), zebrafish zgc:112148 (61% identical), Drosophila melanogaster CG5021 (47% identical), Caenorhabditis elegans C34D4.4 (36% identical). Paralogues in human: TVP23C (95% identical), TVP23A (56% identical).
Diseases named in the same sentence as TVP23B in open-access papers:
TVP23B is named in the same sentence as 4 diseases in open-access papers, as found by Europe PMC text mining. Sharing a sentence is not in itself a finding about the gene and the disease. The quoted sentences say what the papers report.
colitis (1 paper, 2023). Inflammation of the colon. "Through this screen, we found that loss of Tvp23b leads to hypersensitivity to DSS-induced colitis." (PMID 37339972, 2023).
congenital disorder of glycosylation (1 paper, 2023). Congenital disorder of glycosylation (CDG) is a fast growing group of inborn errors of metabolism characterized by defective activity of enzymes that participate in glycosylation (modification of proteins and other macromolecules by adding and processing of oligosaccharide side chains). "The overall effect of TVP23B deficiency is analogous to congenital disorders of glycosylation (CGD)." (PMID 37339972, 2023).
infectious colitis (1 paper, 2023). A viral or bacterial infectious process affecting the large intestine. "Using ENU based germline forward genetics and CRISPR/Cas9 germline targeting, we demonstrated that a damaging mutation in the Golgi resident protein TVP23B renders mice susceptible to DSS-induced and infectious colitis, which is presumably due to the same mucus defect." (PMID 37339972, 2023).
TVP23B also shares sentences with these, for which no sentence is quoted: epilepsy (1 paper).